AR (androgen receptor)
Diseases named in the same sentence as AR in open-access papers (continued):
Sharing a sentence is not in itself a finding about the gene and the disease.
breast carcinoma (continued). "In summary, we demonstrated a possible mechanism mediated by BQ to induce tamoxifen resistance in ER+ve breast cancer through AR-mediated signaling." (PMID 35054486, 2022). "In AR+/ER− breast cancer, AR is a biomarker of radioresistance and inhibition or knockdown of AR results in radiosensitisation, partially through the inhibition of a non-homologous end-joining (NHEJ) repair-mediated response." (PMID 35618789, 2022). "The authors concluded that this study provided a strong preclinical rationale for the development of AR PROTACs to treat AR + human breast cancer." (PMID 35702041, 2022). "Extensive crosstalk between GR signaling and other steroid receptors, including ER, PR, androgen receptor (AR), and mineralocorticoid receptor (MR), have been described in breast cancer in detail." (PMID 35761157, 2022). "Collectively, these results suggest that Kindlin-2 association with AR is critical for Src-mediated AR Tyr-534 phosphorylation, AR nuclear translocation, AR target gene expression, breast cancer cell proliferation and migration." (PMID 35595729, 2022). "As another hormonal receptor, the androgen receptor (AR) was expressed in 70–85% of all breast cancer cases, and that ratio was about 10–63% in triple-negative breast cancer (TNBC), which did not express ER, PR, or HER2." (PMID 36232774, 2022). "Applying AR expression status to guide treatment in different breast cancer sub-types has been suggested." (PMID 35053220, 2022). "The majority of breast cancer often express androgen receptor(AR), with 84%to 95% in ER+ breast cancer, 50% to 63% in ER−/HER2+ and 10% to 53% in triple negative breast cancer (TNBC)." (PMID 35399920, 2022). "Our studies provide a rationale for targeting the Kindlin-2-Src-AR signaling axis in therapeutic control of breast cancer progression." (PMID 35595729, 2022). "Apocrine carcinoma is a special subtype of breast cancer characterized by apocrine metaplasia, histologically, and the activation of the AR pathway, molecularly." (PMID 35329934, 2022). "The role of AR in HR–positive breast cancer is controversial, particularly with regard to the relationship between AR and resistance to endocrine therapy." (PMID 36556209, 2022). "Bicaluamide can effectively control androgen level by combining with AR, thus promoting breast cancer cell death." (PMID 35311116, 2022). "First, functional AR and ER activity was validated by western blot and through qPCR experiments in AR+/ER+ breast cancer cell lines (CAMA-1, ZR-75-1, BT-474)." (PMID 35618789, 2022). "The literature reports that male breast cancer patients represent approximately 1% of the patient population, and almost all are ER+ AR+." (PMID 36556209, 2022). "AR, like ER and PR, is a steroid receptor that is expressed in normal breast as well as 60%–90% of all breast cancer." (PMID 36405944, 2022). "In the current study, we have demonstrated that Kindlin-2 is crucial for AR signaling and breast cancer progression." (PMID 35595729, 2022). "On the other hand, the immunohistochemical AR status in primary breast carcinoma tissues correlates with longer disease-free and overall survival in breast cancer patients receiving endocrine therapies (SERM: 71.8%; SERM followed by AI: 25.2%; AI: 2.9%)." (PMID 37435447, 2022). "AR is highly expressed in HER2 enriched (HER2E) breast cancer, and HER2E breast cancers are hormonally driven, either by ER in ER+ HER2E tumors or by AR in ER- HER2E tumors." (PMID 35207749, 2022). "Using a 1 h pretreatment with apalutamide, darolutamide or seviteronel, we further assessed radiosensitisation in AR+/ER+ breast cancer cells." (PMID 35618789, 2022). "We next investigated the effects of Kindlin-2 on AR tyrosine phosphorylation and breast cancer progression in vivo." (PMID 35595729, 2022). "AC is a rare type of breast cancer that is usually ER-negative, PR-negative, and AR-positive, and 30% show amplification of HER2." (PMID 36084385, 2022).
breast carcinoma (continued). "The comprehensive molecular analyses of breast cancer tumours have demonstrated a subset of TNBC resembling molecular apocrine or luminal androgen receptor (LAR) tumours with androgen receptor activation and its downstream effects." (PMID 35877237, 2022). "Collectively, these results suggest that the association of Kindlin-2 with Src, like that with AR, is critical for regulation of AR signaling, breast cancer cell proliferation and migration." (PMID 35595729, 2022). "Targeting AR alone or other therapeutic agents provides alternatives to existing therapy for breast cancer." (PMID 35053220, 2022). "The androgen receptor (AR) is expressed in most breast cancers (70–85%) and is found primarily in ER-positive tumors." (PMID 35884530, 2022). "Recent data have also suggested that AR functions as a tumour suppressor in AR+/ER+ breast cancers, and ongoing trials are investigating the use of AR agonists (NCT01616758, NCT02463032)." (PMID 35618789, 2022). "AR expression in ER + ve/HER2-ve breast cancer was significantly associated with better breast cancer-specific survival (BCS), recurrence-free survival (RFS), and OS; however, AR expression became a poor prognostic factor in ER-ve patients." (PMID 35053220, 2022). "AR is a widespread molecular marker across various breast cancer subtypes, and approximately 70–90% of luminal–type breast cancers express AR." (PMID 36556209, 2022). "They found that ER–positive breast cancer patients with AR/ER ≥ 2 had higher cell proliferation gene expression levels." (PMID 36556209, 2022). "Patients diagnosed with ER−/AR+ breast cancer were 9 years older than those with ER−/AR− breast cancer, which is consistent with previous findings." (PMID 36232774, 2022). "Upon breast cancer subtype breakdown, AR positivity showed similar results of improved prognosis in both ER positive and TNBC patients." (PMID 35711833, 2022). "In ER-/AR+ molecular apocrine breast cancer cells, FOXA1 binding sites overlap with 98% of AR binding sites." (PMID 36497214, 2022). "In contrast, AR has been found to increase MYC expression in several PCa cell lines, and in AR-positive apocrine breast cancer cells." (PMID 34911936, 2021). "Metroxyprogesterone acetate (MPA), a first-generation progestin and a PgR agonist, is another treatment option; however, MPA also has binding affinity for other steroid receptors such as AR, and the anti-tumor mechanism in breast cancer is still unclear." (PMID 34070471, 2021). "The plastin-2 (LCP1) gene was shown to be relevant in MBC due to its FC values and its responsiveness to testosterone in androgen receptor (AR)-positive prostate and breast cancer cells." (PMID 33656060, 2021). "More recently, there has been a resurgence of interest in the role of the AR signalling axis in ER+ breast cancer." (PMID 34638457, 2021). "The AR pathway is critical in AR+ breast cancer, functionally interacting with multiple classic oncogenic signaling pathways." (PMID 34575114, 2021). "Combining the total features selected from three strategies, we finally got 27 features and 34 features for predicting AR expression and molecular subtype of breast cancer, respectively." (PMID 34490107, 2021). "Of them, the top risk-associated TFs included well-known breast cancer master regulators, FOXA1, ESR1, and AR, and other related TFs, such as SIN3AK and TCF7l2." (PMID 34518541, 2021). "Androgen receptor (AR), a steroid hormone receptor, is gaining attention as both a prognostic marker and a potential therapeutic target in breast cancer." (PMID 33435254, 2021).
breast carcinoma (continued). "Clearly, p68 regulates AR expression and consequently the function of AR in promoting breast cancer cell proliferation in response to androgen stimulation." (PMID 34659545, 2021). "The androgen receptor (AR) is expressed in up to 80% of all breast cancers; however, it is more commonly co-expressed in primary and metastatic ER+ cancers (90% and 75%, respectively)." (PMID 33671468, 2021). "Intriguingly, it is also demonstrated that HOTAIR levels are strongly correlated to androgen receptor (AR) status in breast cancer." (PMID 34073224, 2021). "It has been demonstrated that inhibition of USP14-mediated androgen receptor (AR) deubiquitination contributes to the downregulation of AR proteins and suppression of AR-related signaling pathways, such as Wnt/β-catenin in breast cancer." (PMID 33791305, 2021). "AR and ER co-localize at select genomic loci within the nuclei of breast cancer cells, and functional crosstalk between the hormone receptors has been well-described." (PMID 34638457, 2021). "Currently, new therapeutic strategies focus on PR and AR steroid receptors, and their ligands in various subtypes of breast cancer." (PMID 34070921, 2021). "Therapeutically, the development of selective androgen receptor modulators (SARMs), such as enobosarm and RAD140, now offers a novel approach for targeting AR in breast cancer." (PMID 34638457, 2021). "Both genetic knockdown and pharmacological inhibition of USP14 inhibits the proliferation and induces the apoptosis of AR-positive breast cancer cells." (PMID 35069211, 2021). "USP14 is required for enhancing AR+ breast cancer cell proliferation through deubiquitination and stabilization of AR." (PMID 34575114, 2021). "Taken together, our findings reveal an important new mechanism of regulation through p68-PDGFRβ-AR axis, resulting in enhanced cancer cell proliferation and migration, and therefore progression of breast cancer." (PMID 34659545, 2021). "Androgen receptor (AR) expression occurs in up to 86% of human epidermal growth factor receptor 2-positive (HER2+) breast cancers." (PMID 33591468, 2021). "In previous studies performed at our institution, it has been demonstrated that neoplastic cells in male breast cancer acquire additional copies of X chromosome with consequent AR polysomy." (PMID 33534004, 2021). "The prognostic value of AR expression in breast cancer has been evaluated in multiple breast cancer cohorts." (PMID 34234742, 2021). "In general, AR has been considered as a promising target for both prostate and breast cancers, and AR degradants have more potential to overcome drug resistance as compared with AR antagonists." (PMID 34488823, 2021). "Our results suggest that both p68 and PDGFR-β regulate AR expression and control androgen dependent proliferation in breast cancer cells." (PMID 34659545, 2021). "In this study, we explored candidate serum factors that reflect tumor AR activity to support development of noninvasive serum biomarkers of AR activity in breast cancer." (PMID 34736512, 2021). "The effect of GT0918 on AR protein expression was evaluated in AR expression breast cancer cells and in breast cancer xenograft model." (PMID 34392453, 2021). "A feedback loop has been recognized between these genes in breast cancer cells, in which androgen agonists of AR can increase expression of miR-9-5p." (PMID 34831421, 2021). "Further work would be required to confirm the relative contribution of AR to the actions of 27OHC on breast cancer cells." (PMID 35011656, 2021). "In the following section, this review will elaborate the current knowledge on the role of breast cancer associated SHR members (specially emphasizing ER, PR, and AR) in oncogenesis of breast through deregulation of cell cycle." (PMID 33777765, 2021). "Androgen-inhibiting therapies, like estrogen inhibiting therapies for breast cancer, are largely divided into two categories: anti-AR therapies and therapies inhibiting androgen production." (PMID 34070471, 2021).
breast carcinoma (continued). "This review summarizes the recent findings of a vast array of studies conducted on androgen receptor-positive triple-negative breast cancer (AR-positive TNBC) to provide a better understanding of this specific breast cancer subgroup." (PMID 33915941, 2021). "Expression of the secreted factors was regulated by AR activation in the majority of breast cancer cell lines." (PMID 34736512, 2021). "More so, several reports indicate that other subunits of the Mediator complex, which are actively involved in regulating estrogen and androgen receptor gene expression, are altered in some endocrine malignancies, such as prostate and breast cancer." (PMID 35096564, 2021). "We further developed machine learning models with those selected radiomics features to differentiate molecular subtype and AR expression in breast cancer." (PMID 34490107, 2021). "In recent years, deep-sequencing techniques applied to blood samples have shown that AR pathways are activated in circulating tumor cells from bone-predominant breast cancer." (PMID 34736512, 2021). "The similarities between AR/ER signalling in prostate and breast cancer extend to mechanisms of therapy resistance; indeed, most therapy-resistant cases of BC and PC exhibit alterations to the AR/ER signalling axes that enhance oncogenic signalling." (PMID 34209750, 2021). "A phase II trial of bicalutamide tested 424 patients with ER/PR-negative breast cancer for their AR status and found 12% of them to be AR-positive (immunohistochemistry > 10% nuclear staining)." (PMID 34448553, 2021). "It is also now clear that, in addition to oestrogens, ER function is modulated by other steroid receptors, with the interaction between ER and both PR and AR being the best-characterized models of nuclear receptor crosstalk in breast cancer." (PMID 34638457, 2021). "Multi-parametric MRI-based radiomics combining with machine learning approaches provide a promising method to predict the molecular subtype and AR expression of breast cancer non-invasively." (PMID 34490107, 2021). "In this single-arm phase II study of enzalutamide plus trastuzumab in heavily pretreated patients with advanced HER2+ AR+ breast cancer, CBR24 was 24% in the primary analysis set, with a BORR of 5%." (PMID 33591468, 2021). "In recent years, AR has been proved to be widely expressed in breast cancer and was considered as a significant prognostic biomarker and therapeutic target in breast cancer." (PMID 34490107, 2021). "On the other hand, in the ER-AR + breast cancer cells, AR complex binds to androgen-related element (ARE) in the nucleus and leads to cell proliferation." (PMID 34392453, 2021). "In contrast, the role of AR in breast cancer is controversial, with studies advocating for the use of both AR agonists and antagonists for treating naïve and resistant disease." (PMID 34680352, 2021). "Here we identified PSA, ZAG and PIP as candidate biomarkers reflecting tumor AR activity in breast cancer." (PMID 34736512, 2021). "AR is a member of the steroid hormone receptor superfamily of ligand-activated transcription factors and is overexpressed in 70–90% of breast cancers." (PMID 34490107, 2021). "More recently, anti-AR therapy has been tested in males with breast cancer and in small series of female breast cancer patients with promising but not always consistent results." (PMID 33534004, 2021). "The role of AR signaling depends on ER positivity and negativity in breast cancer, acting as a potential tumor suppressor with ER positivity but as a potential oncogene with ER negativity." (PMID 33799951, 2021). "The androgen receptor (AR) has been demonstrated to be widely expressed in approximately 70% of patients with breast cancer." (PMID 35069211, 2021). "Our study explored the feasibility of the MRI-based radiomics features for predicting the molecular subtype and AR expression of breast cancer." (PMID 34490107, 2021).
breast carcinoma (continued). "According to the safety, tolerability, and pharmacodynamics analysis, GT0918 shows preliminary signs of clinical activity in AR + breast cancer, thereby warranting further evaluation." (PMID 34392453, 2021). "It is known that MPA binds to multiple steroid hormone receptors, such as PR, mPR, GR, and AR, and promotes the proliferation of breast cancer cells." (PMID 34779589, 2021). "We demonstrate that p68 and PDGFR-β co-regulate AR expression and promote androgen-mediated proliferation in breast cancer cells." (PMID 34659545, 2021). "NFIX and HDAC2 have been identified as co-factors of AR in prostate and breast cancer cells, respectively." (PMID 34831421, 2021). "The expression levels of candidate factors are closely correlated with a gene signature representing tumor AR activity in all breast cancer subtypes." (PMID 34736512, 2021). "PSA expression is stimulated by AR and was shown to indicate more benign forms of breast cancer, lower histological grade and ER positivity, other studies report on the contrary." (PMID 34638264, 2021). "After LASSO-RFE fusion feature selection, the seven and the five most optimal radiomics features were selected for predicting molecular subtype and AR expression of breast cancer, respectively." (PMID 34490107, 2021). "Breast cancer tissue expresses sex steroid hormone receptors such as estrogen (ER), progesterone (PR) and androgen (AR) receptors in cancer tissue." (PMID 34070921, 2021). "AR has been shown to differentially affect the metastasis of prostate and breast cancers, through distinctively changing vasculogenic mimicry (VM) formation." (PMID 34831421, 2021). "AR is expressed in up to 85% of ER+ breast cancer and is an independent clinico-pathological prognostic factor associated with favourable outcomes in this setting." (PMID 34638457, 2021). "An important correlation also exists between germ-line mutations in breast cancer susceptibility genes 1 and 2 (BRCA1 and BRCA2), which are associated with a 40–85% lifetime breast cancer risk, and AR structure and transcriptional activity." (PMID 35008851, 2021). "Considering these biological similarity that breast cancer and PCa both are hormone-sensitive disease and are related to androgen receptor pathway, we presumed that Del-1 protein would be highly expressed in patients with PCa than benign prostatic tissue." (PMID 33901217, 2021). "Our predictive model can differentiate molecular subtype and AR status in breast cancer non-invasively and guide individualized treatment." (PMID 34490107, 2021). "We identified PSA, ZAG and PIP as candidate biomarkers reflecting tumor AR activity in breast cancer." (PMID 34736512, 2021). "In fact, AR is the most commonly expressed nuclear receptor in breast cancer overall and is overexpressed in 62% of breast tumor samples." (PMID 34638264, 2021). "Androgen receptor (AR) is expressed in more than 60% of breast cancer and 90% of ER-positive tumors." (PMID 34066808, 2021). "In recent years, the androgen receptor (AR) pathway has received increased attention as a potential target in breast cancer." (PMID 34392453, 2021). "AR is expressed in about 70%-90% of breast cancers and the immunohistochemical expression level of AR varies from 10% to 90% in TNBC." (PMID 34745934, 2021). "Despite the favorable prognostic role of AR in ER positive breast cancer, clinical studies have shown a subset of ER+AR+ tumors with a relative higher expression of AR compared to ER, often develops endocrine resistance when treated with tamoxifen." (PMID 34234742, 2021). "GSEA analysis suggests that these candidate factors correlate with AR in a considerable number of breast cancer patients across breast cancer subtypes." (PMID 34736512, 2021). "Due to the therapeutic and prognostic value, more attentions have been given to the study of AR expression in breast cancer in clinical practice." (PMID 34490107, 2021).